LEP (leptin)
Diseases named in the same sentence as LEP in open-access papers (continued):
Sharing a sentence is not in itself a finding about the gene and the disease.
Obesity (continued). "However, unlike the tight relationship present between obesity and serum leptin levels in mice, human obesity seems to be associated with more possible derrangements from leptin deficiency to leptin resistance." (PMID 18828917, 2008). "The specific expression of Fsp27 in adipose tissue prompted us to check whether levels of Fsp27 protein were correlated with the development of obesity by examining the levels of Fsp27 in the WAT of leptin-deficient ob/ob mice." (PMID 18682832, 2008). "Similarly, in hormones, leptin (P≤ 0.001), insulin (P≤0.001) and glucagon (P≤0.001), and GH (P=0.003) were associated with obesity." (PMID 20300294, 2008). "Although leptin is effective at reducing food intake and body fat in leptin-deficient and normal rodents, it is relatively ineffective in doing so in mice with diet-induced obesity." (PMID 17448988, 2007). "However, in ob/ob mice (who congenitally lack leptin, leading to obesity), leptin deficiency exaggerates the direct inhibitory effect of NPY neurones on POMC neurones in the arcuate nucleus, an effect independent of the actions of GABA." (PMID 17764572, 2007). "As obesity and obesity-linked disorders such as type II diabetes are associated with leptin resistance at the level of the blood brain barrier, it is likely that CNS insensitivity to leptin plays a role in the cognitive impairments in these individuals." (PMID 18024215, 2007). "If true, this “altered wiring” could, in part, explain the profound, early-onset obesity seen in leptin deficient children." (PMID 17448988, 2007). "Another possibility is that other hormones produced by the adipocytes, such as leptin, may play a critical role in the increased breast cancer risk associated with obesity." (PMID 17229323, 2007). "We hypothesized that genetic variations, leading to an altered expression or function of SOCS3 could affect energy homeostasis through an influence on leptin signaling and thus predispose an individual towards the development of obesity." (PMID 17445271, 2007). "However, even if such a leptin-based mechanism is involved in determining subsequent differences in susceptibility to diet-induced obesity, understanding the role of the developing adipose tissue as the source of the leptin surge remains a key factor." (PMID 16733553, 2006). "Obesity in both rodents and humans is generally associated with elevated leptin levels." (PMID 16300680, 2005). "We therefore asked whether diet-induced obesity, which is associated with significantly increased leptin levels and more closely resembles the most common form of human obesity than genetically modified models, would have an impact on innate immune functions." (PMID 15813957, 2005). "However, leptin mutations only account for a small fraction of obesity in humans with the majority of obesity linked to overnutrition and reduced energy expenditure." (PMID 15813957, 2005). "Here we present evidence that obesity and variants in the LEP gene may be important in the pathogenesis of NHL." (PMID 16160698, 2005). "Importantly, low leptin as observed with sleep loss has a greater impact on appetite than high leptin levels, which are associated with leptin resistance, as occurs with obesity." (PMID 15602591, 2004). "Thus they suggest that serum TGs are likely a major cause of the leptin resistance seen in both obesity and starvation." (PMID 15530168, 2004). "Lately, however, pharmacological and genetic ablation of NG2-glia in the adult ME has led to obesity with loss of leptin responsiveness, suggesting that weight gain induction caused by X-irradiation in the ME may be due to the loss of oligodendrocyte progenitor cells (OPCs) following irradiation." (PMID 41118118, 2026). "For rs328, the effect on leptin also differs by sex, with obese males carrying the CC genotype exhibiting higher leptin levels than females, suggesting that this variant may contribute to sex-specific mechanisms in the early pathogenesis of obesity." (PMID 41598432, 2026).
Obesity (continued). "Furthermore, high blood pressure and high leptin levels are associated with obesity." (PMID 40699839, 2025). "On the other hand, obesity is also associated with chronic low-grade inflammation, insulin resistance, altered adipokine profiles—including increased leptin and decreased adiponectin—and changes in drug pharmacokinetics, all of which may negatively affect cancer prognosis." (PMID 41010995, 2025). "In addition to regulating energy balance and glucose and lipid metabolism, leptin and adiponectin, which are mostly produced by adipocytes, also modulate inflammation and may be implicated in the link between obesity and neuronal function." (PMID 40542063, 2025). "Although these data indicate changes related to promoting food intake inhibition, this offspring also had a remarkable reduction in leptin levels, suggesting that changes in leptin signaling and the melanocortin system postnatally could be related to an increased risk of developing obesity." (PMID 40474775, 2025). "Nonsyndromic obesity is primarily associated with genetic mutations to factors involved in the leptin-melanocortin pathway and presents as a disruption to energy homeostasis and its monogenic form affects approximately 5% of the population with early-onset obesity." (PMID 40522819, 2025). "Furthermore, inflammation and leptin resistance related to obesity have been linked to ER stress." (PMID 40278960, 2025). "Research findings indicate that the link between visceral adipose tissue and cancer risk may involve systemic mechanisms, such as leptin, glucose, insulin, and inflammatory cytokines, which are systemic markers of obesity-related adipose tissue inflammation and may promote tumor development." (PMID 40007994, 2025). "Multiple studies have shown that the gender differences observed in the relationship between obesity and asthma appear to be linked to hormonal factors during the prepubertal stage (ages 9–11), particularly those related to pro-inflammatory hormones like leptin, adiponectin, and estrogen." (PMID 40426941, 2025). "However, further clinical investigation in this field is necessary to clarify the role of obesity and leptin in MS, as the underlying mechanisms remain unclear." (PMID 40019662, 2025). "Therapeutic strategies aimed at restoring AMPK activation, balancing the effects of ghrelin and leptin, and preserving the integrity of gap junctions represent potential approaches for the treatment of metabolic and inflammatory syndromes associated with obesity." (PMID 41374016, 2025). "Furthermore, the health effects of metabolic factors such as leptin may follow a “U” shaped pattern, where high levels can lead to leptin resistance and obesity, while low levels may be linked to immune dysfunction and infection." (PMID 41048434, 2025). "The main mechanisms involved in obesity-related vitamin D deficiency include decreased bioavailability due to its accumulation in adipose tissue, reduced intestinal absorption, impaired metabolism, decreased liver 25(OH)D synthesis, and the influence of leptin and IL-6 on hepatic VDRs." (PMID 40724644, 2025). "Furthermore, depending on age, obesity is associated with the development of leptin resistance." (PMID 40843663, 2025). "Consequently leptin is elevated in people with obesity and linked to CVD risk." (PMID 40759955, 2025). "Given that leptin resistance is a hallmark of obesity and has been associated with immune dysfunction in SLE, this increase may reflect an adaptive response or, conversely, a potential exacerbation of metabolic dysregulation and chronic inflammation in these patients." (PMID 40292473, 2025). "Key adipokines such as APN, leptin, chemerin, and vaspin regulate macrophage phenotypes and inflammation, and their imbalance not only disrupts adipose homeostasis but also directly serves as molecular bridges for the immunopathological damage in obesity-associated periodontitis." (PMID 41246338, 2025).
Obesity (continued). "Dysregulated leptin signaling has been associated not only with overeating and weight gain but also with altered stress responses and mood disturbances, which may contribute to the increased susceptibility to anxiety disorders observed in obesity." (PMID 40944223, 2025). "Leptin promotes lipid oxidation and appetite regulation, and is essential for preserving muscle mass, although elevated levels may be associated with muscle dysfunction, especially in the context of obesity." (PMID 40648864, 2025). "This combination of effects, enhanced insulin signaling, normalization of leptin activity, and a macrophage shift toward the M2 phenotype, suggests that anthocyanidins hold considerable therapeutic potential for mitigating chronic inflammation associated with obesity and insulin resistance." (PMID 41374016, 2025). "Additionally, leptin is linked to CSD, suggesting that increased leptin levels in obesity may trigger chronic MIG." (PMID 41470814, 2025). "Notably, only TNF-α and leptin were associated with MetS among the obesity group." (PMID 39837875, 2025). "Leptin as anadipokine is a multifunctional protein that may play a role in the pathogenesis ofMASLD by contributing to various metabolic disorders associated with the disease,including obesity, IR, inflammation, hypertension, dyslipidemia, and T2D." (PMID 41165450, 2025). "Although hyperleptinemia is a close indicator of increased adiposity and obesity, which are risk factors for the development of cardiovascular disease, there still exists some uncertainty as to a cause-and-effect relationship between leptin and the development of cardiovascular pathologies." (PMID 38256208, 2024). "The underlying cause may be related to the state of low-grade chronic inflammation; the increased levels of leptin, which determine the production of proinflammatory cytokines; and, finally, the decreased bioavailability of vitamin D associated with obesity status." (PMID 38892680, 2024). "Additionally, the GRGMLA haplotype might be a susceptibility factor for obesity, with significant associations between LEP and leptin receptor (LEP-R), LEP and ghrelin (GHRL), and GHRL and FTO." (PMID 39766314, 2024). "Increased susceptibility to obesity in MO is associated with systemic hyperleptinemia and hypoestrogenism due to compromised ovarian steroidogenesis, largely driven by the inhibitory effects of leptin-Smad7 pathway on Nodal signalling activity in the TC compartment of ovarian follicles." (PMID 39536822, 2024). "Higher leptin concentrations are associated with increased body fat and the female sex, which may partially account for the sex differences observed in the association between obesity and hs-CRP level." (PMID 39519093, 2024). "In obesity, the production of pro-inflammatory adipocytokines causes chronic low-grade systemic inflammation and oxidative stress; in detail, increased leptin may promote renal fibrosis and glomerulosclerosis, while reduced adiponectin is a determinant of albuminuria development." (PMID 38765954, 2024). "Consequently, it is plausible that leptin or leptin resistance may play a role in the cardiovascular complications associated with obesity and diabetes." (PMID 38397015, 2024). "The results of this study may provide an important clue to the systemic effects of small-sized MPs in the mammalian body, as well as additional evidence regarding the molecular mechanisms involved in the impact of MPs on liver function in normal and leptin-deficient induced-obesity mice models." (PMID 38732183, 2024). "Furthermore, obesity is associated with dysregulated leptin production, which may have additional effects on TSH regulation, such as through mechanisms involving leptin resistance." (PMID 38892561, 2024).
Obesity (continued). "Obesity has also been associated with the altered follicular fluid, the critical environment for oocyte development and granulosa cell steroidogenesis, with elevated concentrations of leptin, insulin, triglycerides, inflammation markers (e.g., lactate and C-reactive protein), and oxidative stress." (PMID 38455649, 2024). "Hence this shows that obesity is causing high levels of leptin in the NOA group." (PMID 38356829, 2024). "Therefore, the combination of high levels of leptin and serum triglycerides may be a marker of obesity “at risk”." (PMID 39684379, 2024). "The discovery of leptin as a regulator of hunger and satiety by signaling through the hypothalamus in the CNS led to the consideration that high levels of leptin may lead to weight loss in people with obesity." (PMID 38206766, 2024). "Therefore, our results indicate that these associations are dependent of obesity status and that leptin could be a better predictor of cardiometabolic health indices in NW mothers." (PMID 38668349, 2024). "Notably, we observed that high saturated fat intake was associated with increased IL-6 levels (OR = 2.03, 95% CI = 1.00–4.11, p < 0.047), whereas high total fat intake was associated with increased leptin levels (OR = 2.14, 95% CI = 1.12–3.38, p < 0.021) in participants with obesity." (PMID 39700087, 2024). "This indicates that, although leptin increases with obesity, it may be, that which causes obesity or excess body fat, which can exist in normal-BMI individuals, often termed TOFI (thin on the outside, fat on the inside), also causes hyperleptinaemia and hyperinsulinaemia." (PMID 39062126, 2024). "By synthesizing recent and past findings on the molecular pathways involved in leptin resistance and their implications for cognitive function, this review aims to identify potential therapeutic targets to address cognitive deficits linked to leptin resistance in obesity." (PMID 39594988, 2024). "As already reported by several studies, HFD causes hepatic steatosis, obesity-related dysbiosis as well as cardiotoxicity, and an increase in hemodynamic (blood pressure and HR), zoometric (weight), and metabolic variables (glucose, insulin, leptin, and ghrelin)." (PMID 39530003, 2024). "Indeed, leptin deficiency/starvation appears to be associated with immunosuppression via an increase in T-regulatory cells and high levels of leptin as seen in individuals with obesity are implicated in the chronic low-grade inflammation observed via an increase in Th1 T-lymphocytes." (PMID 38538853, 2024). "Moreover, leptin as a key regulator of energy metabolism and the immune system contributes to obesity-linked inflammation as well as influences molecules involved in angiogenesis, proliferation, migration, invasion, and adhesion, particularly in breast carcinogenesis." (PMID 39410536, 2024). "Furthermore, it has been shown that surgical interventions alleviate inflammatory conditions associated with obesity, which is evident from a decrease in serum inflammatory markers such as C-reactive protein, leptin, and soluble receptor 1 for tumor necrosis factor." (PMID 39457606, 2024). "It has been reported that the release of gastric-related hormones may be influenced by H. pylori-induced gastritis, and among these hormones, leptin, hunger hormone, gastrin, and growth inhibitor all affect the susceptibility to diabetes and promote obesity and diabetes." (PMID 38652719, 2024). "However, as BMI increases, there may be a state of leptin resistance and a relative deficiency in women who move into the moderate to severe obesity stage, which may contribute to the risk of pregnancy loss." (PMID 38883610, 2024). "It is noteworthy that the GrimAge clock is estimated based on seven DNAm surrogate markers, including leptin, which is associated with obesity, and may thus be more suitable than older generation clocks for estimating the association between age acceleration and metabolic features." (PMID 38273034, 2024).
Obesity (continued). "In addition, increased leptin observed in obesity may contribute to the heightened risk of CVDs in these patients." (PMID 40988882, 2024). "Furthermore, obesity is associated with elevated circulating levels of aldosterone, which can be secreted directly by adipocytes or released from the adrenal gland in response to leptin." (PMID 39682585, 2024). "Therefore, alterations in leptin and orexin hormonal transport along the I/CSF in obesity may be associated with changes in the brainstem and hypothalamic driving pulsations." (PMID 38553569, 2024). "In this setting, the production of adipocytokines by adipose tissue could also be involved in the relationship between obesity and thyroid cancer; moreover, in particular, increased leptin secretion seems to be associated with a poor prognosis and greater tumor aggressiveness." (PMID 39335476, 2024). "In addition, the loss of leptin-LepRl signaling in the brain is sufficient to promote obesity." (PMID 38933888, 2024). "Overall, we confirmed that greater susceptibility to obesity in mothers leads to impaired ovarian steroidogenesis through decreased Nodal signalling activity and reduced support of steroidogenic machinery in the TC compartment, primarily driven by leptin-mediated upregulation of Smad7." (PMID 39536822, 2024). "Obesity has been shown to be a risk factor for the development of migraine and it is hypothesized that increased levels of inflammatory mediators, increased sympathetic activity, and increased leptin which are associated with obesity might influence the development of migraine." (PMID 38481473, 2024). "Furthermore, obesity-induced leptin resistance confers a higher risk of CVDs in women than men." (PMID 40988882, 2024). "Selective leptin resistance, decreased levels of ghrelin (a hormone associated with hunger), and elevated levels of insulin collectively may play a role in driving the sympathetic activation observed in individuals with obesity." (PMID 39411599, 2024). "Furthermore, chronic elevation may induce a succinate-resistant state, similar to the observed phenomenon of leptin resistance in the context of obesity, where hyperleptinaemia is associated with reduced leptin sensitivity." (PMID 38182909, 2024). "Furthermore, obesity is also associated with high levels of leptin." (PMID 39062791, 2024). "Furthermore, the low-grade systemic inflammation caused by some molecules such as interleukin-6 (IL-6), IL-1β, TNFα, leptin, and adiponectin may play a role in obesity association with KOA." (PMID 39472918, 2024). "Additionally, higher leptin levels were seen associated with an increased likelihood of obesity." (PMID 38189043, 2023). "The long-term clinical outcomes of severe obesity due to leptin signaling deficiency are unknown." (PMID 37659411, 2023). "Condensing this evidence, we can state that pregestational obesity is associated with higher leptin and lower adiponectin concentrations during pregnancy and that more detailed studies are needed to clarify whether the concentrations of other adipokines are altered in maternal obesity." (PMID 37834125, 2023). "Notably, the dynamic regulation of mitochondrial shape in POMC neurons has been previously linked to the ability of POMC neurons to sense leptin, while obesity is associated with a shift toward mitochondrial fragmentation within POMC neurons and a reversible decrease incellular leptin sensitivity." (PMID 38016943, 2023). "Although, LEP and LEPR follow an autosomal recessive mode of inheritance, there is a growing evidence that some variants in the heterozygous state in monogenic obesity genes such as LEP and LEPR could lead to severe childhood obesity, hyperphagia, and pituitary dysfunction." (PMID 37329217, 2023). "Therefore, any treatment that results in a decrease in the level of LEP or hypersensitivity to LEP may be a good strategy to prevent lifestyle diseases, very often associated with obesity." (PMID 37858203, 2023).